NEGR1 (neuronal growth regulator 1)
Diseases named in the same sentence as NEGR1 in open-access papers (continued):
Sharing a sentence is not in itself a finding about the gene and the disease.
dyslexia (4 papers, 2015 to 2023). A learning disorder characterized by an impairment in processing written words. "An association of NEGR1 with dyslexia emerged in a copy number variation analysis in Indian families." (PMID 37895235, 2023). "Previous GWASs have indicated an association of the rs17575184 polymorphism with asthma in children (p = 4 × 10−3), whereas other SNPs in NEGR1 were implicated in body weight regulation and dyslexia." (PMID 34070617, 2021). "Partial deletion of chromosome 1p31.1, only involving the NEGR1 gene, has been observed in two siblings affected by attention deficit hyperactivity disorder and language impairments, but not affected by dyslexia." (PMID 37895235, 2023).
neuroblastoma (4 papers, 2020 to 2023). Neuroblastoma (NB) is the most common solid, extracranial childhood tumor. "We also visualized the NEGR1 protein in N2a neuroblastoma cells after transfection with the FLAG-NEGR1 plasmid." (PMID 37187893, 2023). "Previous studies revealed that NEGR1 is commonly downregulated as a tumor suppressor gene in many cancers, including neuroblastoma, breast, colon, and kidney cancers." (PMID 34737762, 2021). "The ectopic overexpression of Negr1 impairs neuroblastoma growth in vitro and in vivo." (PMID 37765276, 2023). "We found that the IgLON member Negr1 is downregulated in neuroblastoma." (PMID 37765276, 2023). "Additionally, low NEGR1 expression is correlated with a low survival probability in neuroblastoma, according to a previous study." (PMID 32375678, 2020). "Here we describe that Negr1-derived peptides induce ALK downregulation and reduce neuroblastoma progression in vitro and in vivo." (PMID 37765276, 2023). "The treatment with Negr1 protein and derived peptides induce ALK downregulation and halt neuroblastoma progression in vitro and in vivo." (PMID 37765276, 2023).
ovarian carcinoma (4 papers, 2020 to 2025). A malignant neoplasm originating from the surface ovarian epithelium. "Lastly, the serum of patients at different stages of ovarian cancer was analysed to determine differently expressed miRNAs, which were correlated with disease biomarkers, including NEGR1." (PMID 39057097, 2024). "It was proposed that mir-4314 decreased the expression of GRWD1, IP6K1, and NEGR1, with a possible correlation with ovarian cancer onset." (PMID 39057097, 2024). "In ovarian cancer, NEGR1 has been proposed as a tumour suppressor gene." (PMID 32375678, 2020). "NEGR1, which is commonly downregulated in various cancers, inhibits the proliferation and anchorage-independent growth of SKOV-3 ovarian cancer cells, and its depletion promotes migration and invasion." (PMID 39781359, 2025). "Accordingly, NEGR1 was identified as a commonly downregulated gene in various types of human cancers, including CRC, suggesting its contribution to tumor suppression, while NEGR1 overexpression reduced the tumorigenic properties of ovarian cancer cell line SKOV-3 cells." (PMID 34070617, 2021).
type 2 diabetes (3 papers, 2013 to 2025). "Another study on monozygotic twins discordant for type 2 diabetes found NEGR1 being upregulated in adipocytes of type 2 diabetic twins." (PMID 34572334, 2021). "Like type 2 diabetes-associated ADAMTS9 rs4607103, BMI-associated NEGR1 rs2815752 was associated with the phenotype-class of “Ever Smoked” in European Americans." (PMID 23382687, 2013).
Abdominal obesity (2 papers, 2017 to 2018). Excessive fat around the stomach and abdomen. "Disagreement with these findings, gains in copy numbers of LEPR and neuronal growth regulator 1 (NEGR1) gene were associated with a decreased body mass index, waist circumference and risk of abdominal obesity in human." (PMID 30134528, 2018).
autism spectrum disorder (2 papers, 2021 to 2023). A spectrum of developmental disorders that includes autism, and Asperger syndrome. "In addition, NEGR1 and FGFR2 downregulation alters social skill-related behaviours similarly to autism spectrum disorder, in reducing ultrasound vocalizations in pups, causing sensory deficits in a hot plate test in newborns, and lowering social interactions in adults." (PMID 37895235, 2023).
clear cell renal carcinoma (2 papers, 2017). A malignant epithelial neoplasm of the kidney characterized by the presence of lipid-containing clear cells within a vascular network. "Mutations in the NEGR1 gene have been related to Wilms tumor, which leads to malignant process in the kidney, additionally LSAMP promoter has been inactivated by methylation in a considerable amount of clear cell renal carcinomas." (PMID 28210208, 2017).
colorectal cancer (2 papers, 2022 to 2025). A primary or metastatic malignant neoplasm that affects the colon or rectum. "Targeting NEGR1 knockdown is a promising approach for the prediction and treatment of colorectal cancer liver metastases." (PMID 40772228, 2025).
developmental delay (2 papers, 2024 to 2025). "All but one of the documented cases in our study exhibit a NEGR1 deletion, consistently presenting with psychomotor and developmental delays." (PMID 40756776, 2025). "Previous studies have reported similar NEGR1 microdeletions, inherited or of unknown origin, in individuals with developmental delay, ID and autistic features." (PMID 38519481, 2024).
Glucose intolerance (2 papers, 2021 to 2025). Glucose intolerance (GI) can be defined as dysglycemia that comprises both prediabetes and diabetes. "Our results thus far suggest that the presence of Negr1 allows male mice to consume more HF food and hinders the development of glucose intolerance and excessive weight gain." (PMID 34572334, 2021). "Our results suggest that the presence of functional Negr1 allows male mice to consume more HFD and prevents the development of glucose intolerance, liver steatosis, and excessive weight gain." (PMID 34572334, 2021).
kidney cancer (2 papers, 2020 to 2021). Primary or metastatic malignant neoplasm involving the kidney. "According to the Kaplan–Meier survival curves, patients with kidney cancer in the low/medium-expression level group for each of LEPR and NEGR1 genes had a long-time life expectancy in comparison to those in the high-expression level group." (PMID 33299884, 2020). "Underexpressed LEPR, NEGR1, TMEM18, and SH2B1 genes prevented the progression and metastasis of kidney cancer." (PMID 33299884, 2020).
mental disorder (2 papers, 2022 to 2025). A disease that has its basis in the disruption of mental process. "The 1p31.1 locus contains the pleiotropic gene NEGR1, well known for its contribution to a variety of mental disorders." (PMID 33905376, 2022). "Furthermore, some of these genes (e.g., NEGR1, PTBP2, BCL11A, ARNTL, SLC25A12, ADARB1) were identified in a recent study investigating the genetic overlap between AN and mental disorders, further supporting their relevance to AN." (PMID 39971893, 2025). "The list of pleiotropic risk factors acting across a variety of psychiatric disorders includes such well-described candidates as NEGR1, SOX5, SORCS3, DCC, and TCF4 and indicates that MDD and PTSD are part of the greater spectrum of mental disorders with shared genetic liability." (PMID 33905376, 2022).
sarcoma (2 papers, 2022 to 2025). A usually aggressive malignant neoplasm of the soft tissue or bone. "In addtion, in models of breast cancer, sarcoma, and bladder cancer, YAP binds with Smad2/3 to activate different target genes such as neuronal growth regulator 1 (NEGR1), hyaluronan-mediated motility receptor (HMMR), and CTGF." (PMID 40673277, 2025).
anorexia nervosa (1 paper, 2023). A disorder most often seen in adolescent females characterized by a refusal to maintain a minimally normal body weight, an intense fear of gaining weight, a disturbance in body image, and, in postmenarcheal females, the development of amenorrhea. "Still within the realm of psychiatric disorders, altered NEGR1 DNA methylation has been discovered in patients affected by anorexia nervosa." (PMID 37895235, 2023).
attention deficit-hyperactivity disorder (1 paper, 2022). A disorder characterized by a marked pattern of inattention and/or hyperactivity-impulsivity that is inconsistent with developmental level and clearly interferes with functioning in at least two settings (e.g. at home and at school). "In addition, a microdeletion in the NEGR1 gene was described in two siblings who presented cognitive disabilities, attention deficit hyperactivity disorder (ADHD), speech problems, and one of them also had features of autism." (PMID 36552158, 2022).
bipolar disorder (1 paper, 2024). A disorder of the brain that causes unusual shifts in mood, energy, activity levels and the ability to carry out day-to-day tasks. "NEGR1 also shows bipolar disorder-associated reductions in the PsychENCODE brain RNA-seq dataset at the transcript level (ENST00000434200, Log2FC = – 0.822 and P = 0.009)." (PMID 39558356, 2024). "Enrichment analysis of AP1AR-DTOE-induced DEGs in both mice and SK-N-SH cells and bipolar disorder-associated genes revealed that neuronal growth regulator 1 (Negr1), a synaptic adhesion molecule, is a potential target of AP1AR-DT." (PMID 39558356, 2024).
brain cancer (1 paper, 2020). A primary or metastatic malignant neoplasm affecting the brain. "Given the role of NEGR1 in neural development and cancer progression, this gene proves to be an intriguing subject in brain cancer research." (PMID 32375678, 2020).
Brain Tumour (1 paper, 2020). "We therefore explored whether the deletions at the NEGR1 locus could be identified in a larger cohort of 73 pHGG patients collected by the Children’s Brain Tumour Tissue Consortium (CBTTC)." (PMID 32375678, 2020). "It is therefore possible that deletions that negatively affect NEGR1 expression might have modulatory effects on brain tumors and have negative prognostic value." (PMID 32375678, 2020).
bronchitis (1 paper, 2020). An acute or chronic inflammatory process affecting the bronchi. "The SNP rs1620977 on NEGR1 is linked with incidence of bronchitis." (PMID 31888951, 2020).
carpal tunnel syndrome (1 paper, 2026). Entrapment of the median nerve in the wrist that is characterized by numbness, tingling and painful movement. "These included associations with genes involved in neurotransmitter signaling (HTR3A), immune function (HLA-DQB1, BCL11A), extracellular matrix remodeling (COL11A1, ADAMTS17, LOXL4), axon guidance and neural development (DCC, ETV1, NEGR1), and carpal tunnel syndrome (DIRC3)." (PMID 41518141, 2026).
colon cancer (1 paper, 2024). "Specifically, we targeted large genes PRKG1, NEGR1, and MAGI2 in fibroblast line UM-HF1 (HF1) and FHIT and WWOX in lymphoblastoid line GM12878 and colon cancer line HCT116 as model systems for replication stress-associated SV formation." (PMID 39505880, 2024).
coronary artery disease (1 paper, 2021). "Furthermore, NEGR1 has been found to control endothelial integrity in human brain microvessels; LSAMP has been shown to be implicated in the coronary artery disease and both LSAMP and OPCML have been shown to be implicated in the epithelial-mesenchymal transition." (PMID 34203377, 2021).
glioblastoma (1 paper, 2021). The most malignant astrocytic tumor (WHO grade IV). "In glioblastomas, YAP confers invasiveness by upregulating miR296-3p as well as other canonical YAP targets (neuronal growth regulator 1 (NEGR1), matrix metalloproteinase 1 (MMP1), endothelin 1 (EDN1), CYR61, and CTGF)." (PMID 34439395, 2021).
glioma (1 paper, 2022). A benign or malignant brain and spinal cord tumor that arises from glial cells (astrocytes, oligodendrocytes, ependymal cells). "From the transcriptome data analysis results in the public database, it was found that CDK4, PBK, ANGPTL2, TMEM100, and MEX3A were significantly up-regulated in the glioma samples compared with the normal samples, whereas NEGR1 and SLC2A3 were down-regulated in the glioma samples at the mRNA level." (PMID 36358948, 2022). "The role of NEGR1 and TMEM100 in glioma has not yet been reported." (PMID 36358948, 2022).
Hypertension (1 paper, 2021). The presence of chronic increased pressure in the systemic arterial system. "Even though NEGR1 has been associated with many phenotypes in the GWAS Catalog, no GWAS has yet been able to directly link it to hypertension." (PMID 34296082, 2021).
inflammatory bowel disease (1 paper, 2025). A spectrum of small and large bowel inflammatory diseases of unknown etiology. "The KEGG analysis of overlapped gene sets demonstrated that the IL-17 pathway and inflammatory bowel disease were the most affected by Negr1 deficiency in multiple tissues." (PMID 40698360, 2025).
lymph node metastasis (1 paper, 2021). "In terms of lymph node metastasis, differential expression of NEGR1, NTNG1, XPNPEP2, CD109, OPCML, and PRND had statistical significance in the groups of N0 and N1." (PMID 34737762, 2021).
mastitis (1 paper, 2025). Inflammation of breast tissue during lactation or postpartum due to an obstructed duct or infection. "These included genes and QTLs related to somatic cell count and mastitis (CACNA2D1, SEMA5A, NEGR1, PTK2B, CTNNA3), gastrointestinal parasites (PTK2B), and various viral or bacterial diseases." (PMID 41273432, 2025).
multiple sclerosis (1 paper, 2023). A progressive autoimmune disorder affecting the central nervous system resulting in demyelination. "A meta-analysis approach on gene expression data in multiple sclerosis patients’ tissues showed a significant increase in NEGR1 levels, which was interpreted as a leading cause of impaired synaptogenesis." (PMID 37895235, 2023).
myocardial infarction (1 paper, 2022). Gross necrosis of the myocardium, as a result of interruption of the blood supply to the area, as in coronary thrombosis. "This study aimed to determine whether the long-stranded non-coding ribonucleic acid (lncRNA), myocardial infarction-associated transcript (MIAT), could upregulate neuronal growth regulator 1 (NEGR1) by competing for miR-150-5p as a competitive endogenous RNA in a rat SCIRI model." (PMID 36620092, 2022).
Parkinson disease (1 paper, 2023). A progressive degenerative disorder of the central nervous system characterized by loss of dopamine producing neurons in the substantia nigra and the presence of Lewy bodies in the substantia nigra and locus coeruleus. "In synucleinopathies, including Parkinson’s disease, NEGR1 has been indicated as a potential CSF biomarker in mass spectrometry studies, thus implicating relevance for diagnostic and therapeutic applications." (PMID 37895235, 2023).
prediabetes (1 paper, 2021). "The HF diet does promote prediabetes and fat accumulation, which amplifies the metabolic pathways already activated by the absence of Negr1." (PMID 34572334, 2021).
steatosis (1 paper, 2021). Increased lipid within the cytoplasm of cells. "The steatosis-prone phenotype seems to be present in both sexes of Negr1-deficient mice." (PMID 34572334, 2021).
Stroke (1 paper, 2012). Sudden impairment of blood flow to a part of the brain due to occlusion or rupture of an artery to the brain. "The expression of neuronal growth regulator 1 (Negr1), a cell adhesion protein involved in the trans-neural growth-promoting factor in regenerative axon sprouting in the mammalian brain, was recently found to be upregulated by stroke." (PMID 22272763, 2012).
transmissible spongiform encephalopathies (1 paper, 2023). "An association between NEGR1 and transmissible spongiform encephalopathies, fatal neurodegenerative diseases characterised by infectious proteins, has been discovered in rodent models in which substantially decreased levels of NEGR1 have been demonstrated." (PMID 37895235, 2023).
psychiatric disorder (19 papers, 2011 to 2026). A disorder characterized by behavioral and/or psychological abnormalities, often accompanied by physical symptoms. "The NEGR1 gene has been implicated in several psychiatric disorders, and increased NMDA receptor binding density has been demonstrated in vitro in hippocampal slices from Negr1-deficient mice." (PMID 41545566, 2026). "The overlapped PTSD DEPs include downregulated GABAergic genes SLC32A1, NEGR1, and PACSIN1, which we consider are high-confidence PTSD DEPs, especially NEGR1 which is also a risk gene for multiple psychiatric disorders including MDD and SCZ." (PMID 40301990, 2025). "NEGR1 has been implicated in normal brain development and susceptibility to a wide spectrum of psychiatric disorders and in AD pathology in humans." (PMID 30932003, 2019). "We show that Negr1 deficient mice exhibit behavioral alterations and morphological abnormalities in the brain that are similar to the ones observed in psychiatric disorders such as SCZ, ASD and ADHD." (PMID 30932003, 2019). "The in vitro function of NEGR1 together with results from gene associations studies in cognitive and psychiatric disorders, prompted us to examine the role of NEGR1 in neuronal growth and behavior in Negr1-deficient mice." (PMID 29479305, 2018). "Furthermore, a maternal function of these genes might account for differences in the severity or onset of NEGR1- or OPCML-linked psychiatric disorders." (PMID 38540422, 2024). "Therefore, it is important to ask the question of how the alterations of NEGR1 expression may underlie the neuropathology of psychiatric disorders." (PMID 30932003, 2019). "Thus, our results from neuronal growth assays, neuroanatomical analyses and behavioral assessments provide first evidence that deficiency of the psychiatric disease-associated Negr1 gene may affect neuronal growth and behavior." (PMID 29479305, 2018). "This work enhances our understanding of NEGR1’s function in peripheral tissues and its possible involvement in peripheral-central immune crosstalk relevant to psychiatric disorders." (PMID 40698360, 2025). "This study provides new insights into the cellular function of NEGR1 as well as peripheral factors that may contribute to mental illness." (PMID 40698360, 2025). "Variants in NEGR1 have also been associated with alterations in white matter integrity in individuals with psychiatric disorders, independent of obesity-related traits, and with susceptibility to eating disorders." (PMID 41440084, 2025). "However, the two IgLON family members, Negr1 (IgLON4) and LSAMP (IgLON3), which showed more behavioral alterations in the KO mouse model, have been implicated in several psychiatric disorders." (PMID 38370417, 2024).